CPXCR1 (CPX chromosome region candidate 1)
Synonyms: CT77
Tractability: No criterion of Open Targets' tractability assessment is met for any kind of drug.
Gene: Protein-coding gene on chromosome X (88,747,225 to 88,754,785, forward strand). Ensembl gene ENSG00000147183.
Homologues: Orthologues: chimpanzee CPXCR1 (98% identical), mouse Cpxcr1 (43% identical).
Diseases named in the same sentence as CPXCR1 in open-access papers:
CPXCR1 is named in the same sentence as 8 diseases in open-access papers, as found by Europe PMC text mining. Sharing a sentence is not in itself a finding about the gene and the disease. The quoted sentences say what the papers report.
Abdominal obesity (1 paper, 2017). Excessive fat around the stomach and abdomen. "Our results indicate a possible contribution of CNVs in LEPR, NEGR1, ARHGEF4, and CPXCR1 and the intergenic regions 12q15c, 15q21.1a, and 22q11.21d to the development of obesity, particularly abdominal obesity in Mexican children." (PMID 28428959, 2017).
cleft lip (1 paper, 2017). Congenital defect in the upper lip where the maxillary prominence fails to merge with the merged medial nasal prominences. "CPXCR1 is located in Xq21.3, and this region has been associated with the development of cleft lip and cleft palate, though the mechanism by which this disease develops has not been defined." (PMID 28428959, 2017).
cleft palate (1 paper, 2017). Cleft palate is a fissure type embryopathy that affects the soft and hard palate to varying degrees. "CPXCR1 is one among several genes identified in the critical region for X-linked cleft palate." (PMID 28877219, 2017).
Obesity (1 paper, 2017). Accumulation of substantial excess body fat. "In this study, we found significant differences in the copy numbers among children with obesity compared to those in normal weight children for LEPR, NEGR1 ARHGEF4, CPXCR1, and INS and four intergenic regions previously associated with obese children." (PMID 28428959, 2017). "The analysis of CNVs in six regions corresponded to five genes previously associated with obesity, LEPR (intron 2 and intron 3), NEGR1, ARHGEF4, CPXCR1, and INS, and four intergenic regions (1p36.33b, 12q15c, 15q21.1a, and 22q11.21d)." (PMID 28428959, 2017). "For ARHGEF4, we found that children with obesity more frequently showed gains (22.6%) as also observed for CPXCR1 (49.2%), whereas for INS losses occurred most frequently in obese children (25.7%)." (PMID 28428959, 2017). "The purpose of this study was to evaluate the association between CNVs in specific regions of LEPR, NEGR1, ARHGEF4, CPXCR1, and INS and in four intergenic regions (1p36.33b, 12q15c, 15q21.1a, and 22q11.21d) and obesity in Mexican children." (PMID 28428959, 2017).
orofacial cleft (1 paper, 2017). A disorder of facial skeleton that is characterized by cleft lip and/or cleft palate that result in feeding, speech and hearing problems caused by failures during development. "Associations with KLHL4, EFNB1/PJA1, CPXCR1, TBX22, and BCOR were particularly noteworthy because they are involved in syndromes that feature orofacial clefts." (PMID 28877219, 2017).
schizophrenia (1 paper, 2023). A major psychotic disorder characterized by abnormalities in the perception or expression of reality. "A genetic variant near the switch gene CPXCR1 was associated with schizophrenia risk in Japanese males in a replication cohort." (PMID 36982982, 2023). "Seven switch genes, NPAS3, ARHGAP15, LGALS3BP, DPP10, SMYD3, CPXCR1, and HLA-DRB5, were associated with known risk factors for schizophrenia." (PMID 36982982, 2023). "Likewise, NPAS3, ARHGAP15, LGALS3BP, DPP10, SMYD3, CPXCR1, and HLA-DRB5 were associated with known risk factors for schizophrenia." (PMID 36982982, 2023).
cancer (1 paper, 2016). A tumor composed of atypical neoplastic, often pleomorphic cells that invade other tissues. "Less information are available for six of the genes in the panel in relation to cancer namely the ITPRIP, FRMD6, CPXCR1, SLC38A9, MRPL52 and GFRA4." (PMID 27609023, 2016).
CPXCR1 also shares sentences with these, for which no sentence is quoted: colorectal cancer (1 paper).